SKP2 (S-phase kinase associated protein 2)
Diseases named in the same sentence as SKP2 in open-access papers (continued):
Sharing a sentence is not in itself a finding about the gene and the disease.
mantle cell lymphoma (2 papers, 2016 to 2021). Mantle cell lymphoma is a rare form of malignant non-Hodgkin lymphoma affecting B lymphocytes in the lymph nodes in a region called the ``mantle zone''. "Consistently, another study reported that the depletion of Skp2 decreases phosphorylated ATM protein levels in cisplatin-resistant mantle cell lymphoma JeKo-1 cell line and the downstream-acting factors of ATM that directly participates in DNA repair." (PMID 34068643, 2021). "Evidently, Skp2-deficiency is more effective in increasing cisplatin cytotoxicity in cisplatin-resistant cells than the inhibition of ATM, suggesting Skp2 is likely to be a more promising target than ATM in the treatment of cisplatin-resistant mantle cell lymphoma (MCL)." (PMID 34068643, 2021). "Using a mantle cell lymphoma (MCL) model, Lwin and colleagues demonstrated that adhesion of MCL cells to BMSCs resulted in a reversible growth arrest that correlated with a decrease in Skp2 and an increase in p27 levels in the MCL cells." (PMID 27655696, 2016).
Miscarriage (2 papers, 2021 to 2023). A pregnancy that ends at a stage in which the fetus is incapable of surviving on its own, defined as the spontaneous loss of a fetus before the 22th week of pregnancy. "The recurrent miscarriage patients were reported to have reduced expression in the decidual tissues compared to normal pregnant women, and Skp2-deficient mice showed impaired ovarian development and reduced fertility." (PMID 37089937, 2023).
Nephropathy (2 papers, 2012 to 2013). A nonspecific term referring to disease or damage of the kidneys. "TNF-α was reported to enhance mRNA expression of Skp2 in a normal rat epithelial kidney cell line (NRK) but not in control cells, which suggests that TNF-α facilitates the induction of Skp2 in nephropathy." (PMID 23255047, 2013). "However, the target-specific physiological functions of Skp2 have not been fully elucidated in kidney diseases." (PMID 22558406, 2012).
osteoporosis (2 papers, 2023 to 2025). A condition of reduced bone mass, with decreased cortical thickness and a decrease in the number and size of the trabeculae of cancellous bone (but normal chemical composition), resulting in increased fracture incidence. "In this study, we aimed to explore the mechanisms involved in carbamazepine (CBZ) and microRNA (miR)-20a-5p/ubiquitin-specific peptidase 10 (USP10)/S-phase kinase-associated protein 2 (SKP2) axis in osteoporosis." (PMID 37915040, 2023). "qRT-PCR revealed that overexpression of miR-495 significantly reduced SKP2 expression in osteoblasts (all p < 0.05), and SKP2 expression in femur tissues of osteoporosis mice was significantly elevated (all p < 0.05)." (PMID 39972431, 2025). "In the future, we will further verify the mechanism of CBZ and miR-20a-5p/USP10/SKP2 axis in osteoporosis in animal models." (PMID 37915040, 2023). "In this study, we treated BMSCs with CBZ and constructed cell lines that interfered with or overexpressed miR-20a-5p, USP10 and SKP2 to explore the effects of CBZ by regulating miR-20a-5p/USP10/SKP2 axis on osteoporosis." (PMID 37915040, 2023). "Due to time and funding constraints, we only conducted in vitro studies on the mechanism of CBZ and miR-20a-5p/USP10/SKP2 axis in osteoporosis." (PMID 37915040, 2023). "CBZ regulated USP10 through miR-20a-5p to affect the deubiquitination of SKP2 and inhibit osteogenic differentiation, which provided a new idea for osteoporosis treatment." (PMID 37915040, 2023). "Briefly, SKP2 suppressed Runx2 expression in osteoporosis through ubiquitination degradation." (PMID 39972431, 2025). "Therefore, we speculated that miR-495 affected osteoporosis by targeting SKP2 expression." (PMID 39972431, 2025). "Currently, there is no report on the mechanism of CBZ in osteoporosis through the miR-20a-5p/USP10/SKP2 axis, which is first reported in this study." (PMID 37915040, 2023).
ovarian tumor (2 papers, 2014 to 2024). "The expression levels of cyclin E, SKP2, and stathmin increased with the malignant grade of ovarian tumors and group II had the highest expression levels." (PMID 25106448, 2014). "In the present study, we detected SKP2 protein expression in ovarian tumors." (PMID 25106448, 2014). "This study is to compare the expression of cyclin E, S-phase kinase-associated protein 2 (SKP2), and stathmin between PGCCs with budding and control HEY cells, and determine the clinicopathological significance of cell cycle-related protein expression in ovarian tumors." (PMID 25106448, 2014). "When SKP2 or YAP are removed, lipid oxidation is inhibited during the ferroptosis inducer.Therefore, the Hippo pathway may be a major target in ovarian tumor cell ferroptosis and play a crucial role in controlling the susceptibility of ferroptosis inducers to ovarian tumor ferroptosis." (PMID 39192972, 2024).
pituitary tumor (2 papers, 2013 to 2020). A benign or malignant neoplasm affecting the pituitary gland. "The role of Skp2 as an oncogene responsible for down regulation of p27kip1 protein levels is well established in a wide variety of tumors, including pituitary tumors." (PMID 23667519, 2013). "Our results suggest a significant inverse correlation between Skp2 and p27kip1 protein levels, mainly in beta-carotene stimulation for 48 h, which might be associated with anti-proliferative and pro-apoptotic effects induced by beta-carotene treatment on pituitary tumor cells." (PMID 23667519, 2013). "We examined the possibility of a correlation between Skp2 and p27kip1 expression in ACTH-secreting pituitary tumor cells under carotenoids stimulation." (PMID 23667519, 2013).
prostatic hyperplasia (2 papers, 2013 to 2026). "Also attesting the importance of Skp2 in tumor development, there is a report using transgenic mouse model where Skp2 overexpression induced prostatic hyperplasia, dysplasia, and low-grade carcinoma." (PMID 23385514, 2013).
psoriasis (2 papers, 2024 to 2025). An autoimmune condition characterized by red, well-delineated plaques with silvery scales that are usually on the extensor surfaces and scalp. "The key cell cycle regulatory protein F-box protein S-phase kinase-associated protein 2 (SKP2) was significantly downregulated, along with the psoriasis-associated proliferation marker WNT5a, identified as a SKP2 downstream target." (PMID 40806307, 2025). "Recent studies have also reported increased SKP2 expression in the lesional skin of psoriasis patients, as well as in the IMQ mouse model." (PMID 40806307, 2025).
pulmonary arterial hypertension (2 papers, 2010 to 2016). Pulmonary arterial hypertension (PAH) is a group of diseases characterized by mean pulmonary artery pressure >20 mmHg and elevated pulmonary arterial resistance leading to right heart failure. "Beta-estradiol application reversed the reduction of p27kip1, elevation of Skp-2 and Akt-P, accompanied with the attenuation of pulmonary hypertension and PVSR induced by hypoxia." (PMID 21182801, 2010). "Aiming to know whether p27kip1 and Skp-2 were involved in chronic hypoxia-induced pulmonary hypertension and artery remodeling, the protein levels of p27kip1 and Skp-2 in the 4 experimental groups were compared." (PMID 21182801, 2010). "Taken together, our study indicates that AMPKα2 isoform plays an important role in regulation of PASMCs proliferation by modulating mTOR/Skp2/p27Kip1 axis, and suggests that activation of AMPKα2 might have potential value in the prevention and treatment of pulmonary arterial hypertension." (PMID 27258250, 2016).
rectal cancer (2 papers, 2016 to 2021). A primary or metastatic malignant neoplasm that affects the rectum. "While higher level of immunostaining of SKP2 has also been shown to be in poor response to radiotherapy in oral, nasopharyngeal and rectal cancers." (PMID 27317767, 2016).
renal fibrosis (2 papers, 2013 to 2021). A final common manifestation of a wide variety of chronic kidney diseases characterized by glomerulosclerosis and tubulointerstitial fibrosis. "In the progressive kidney obstruction mouse model, Skp2 deficiency suppresses renal fibrosis and the progression of renal fibrosis is partially recovered by Skp2/p27-double deficiency." (PMID 34198949, 2021). "In deficient mice, α-SMA-positive myofibroblasts also decrease which suggests that Skp2 is involved in renal cell proliferation and epithelial-to-myofibroblast transition during the progression of renal fibrosis." (PMID 34198949, 2021). "We suggest that the progression of renal damage is stopped at an early stage by Skp2 deletion, reducing the extent of renal fibrosis in UUO kidneys of Skp2−/− mice." (PMID 23255047, 2013). "In the UUO kidneys of Skp2−/− mice, extracellular matrix production, inflammation, and renal fibrosis may be ameliorated by p27 accumulation." (PMID 23255047, 2013).
synovial sarcoma (2 papers, 2022 to 2024). "Previously, we have shown that SKP2 plays a crucial role in maintaining a mesenchymal state and enhancing tumor-initiating properties in synovial sarcoma." (PMID 38355807, 2024). "The result of treatment of synovial sarcoma cells was with Skp2 inhibitor flavokawain A (FKA) showing that Skp2 inhibitor can induce cell growth cycle arrest." (PMID 35845132, 2022). "Since we previously showed that C1 worked synergistically with a cytotoxic agent in synovial sarcoma cells, we tested whether SKP2 inhibitors have a synergistic effect with doxorubicin, a conventional chemotherapy commonly used in OS." (PMID 38355807, 2024).
T-cell leukemia (2 papers, 2020 to 2023). A malignant disease of the T-lymphocytes in the bone marrow, thymus, and/or blood. "Given the role of Notch in T-cell leukemogenesis and the converging effects of Notch and IL-7 on SKP2, we investigated the role of SKP2 in T-ALL leukemogenesis in vivo by using a Notch-induced T-cell leukemia mouse model." (PMID 31772299, 2020). "In addition, in T cell leukemia cell line TAIL7, two Skp2 inhibitors, SZL-P1-41(30 μM) and SKPin C1(2.4 μM) exhibited significantly different performances." (PMID 37089937, 2023).
thyroid cancer (2 papers, 2011 to 2023). "In human thyroid carcinomas, constitutive signaling of the MAP kinase cascade contributes to the development of thyroid cancer promoted by activated RAS and BRAF onco-proteins and that this occurs, at least in part, by compromising the Skp2-dependent degradation pathway." (PMID 21386910, 2011).
Ureteral obstruction (2 papers, 2012 to 2013). Obstruction of the flow of urine through the ureter. "In Skp2−/− mice, renal damage caused by unilateral ureteral obstruction (UUO) was ameliorated by p27 accumulation, mainly in tubular epithelial cells." (PMID 23255047, 2013). "We previously reported an increase in Skp2 in progressive nephropathy and amelioration of unilateral ureteral obstruction (UUO) renal injury associated with renal accumulation of p27 in Skp2−/− mice." (PMID 22558406, 2012).
adenoma (1 paper, 2020). A neoplasm arising from the epithelium. "The potential carcinogenic role of SKP2 was suggested by the findings that SKP2 expression was undetectable in normal colon mucosa but significantly increases from adenoma to carcinoma, hoping these patients to get benefit from targeted therapy." (PMID 32856866, 2020). "Correlation of SKP2 expression in both types of adenoma (tubular and tubulovillous) and in different grades of associated dysplasia (low and high) showed no statistical significant difference." (PMID 32856866, 2020). "SKP2 positivity was detected in 26.7% and 45% of adenomas and CRCs respectively, while other studied groups were negative." (PMID 32856866, 2020). "A potential carcinogenic role of SKP2 was suggested by the findings that SKP2 expression was undetectable in normal colonic mucosa but significantly increases from adenoma to carcinoma, hoping adenoma patients to get benefit from targeted therapy." (PMID 32856866, 2020). "Regarding adenoma group, SKP2 positivity was detected in 26.7%." (PMID 32856866, 2020). "Regarding expression of SKP2 in adenoma, no statistical significant difference was detected between both types (tubular and tubulovillous) (p=0.310) nor between grades of associated dysplasia." (PMID 32856866, 2020). "SKP2 immunoreactivity was found in 18/40 (45%) of CRCs and 4/15 (26.7%) of adenomas with high statistical significant difference compared to the other groups (p=0.000) which were negative for SKP2." (PMID 32856866, 2020).
Azoospermia (1 paper, 2006). Absence of any measurable level of sperm,whereby spermatozoa cannot be observed even after centrifugation of the semen pellet. "Male Skp2-/- mice exhibited a markedly reduced number of spermatozoa (azoospermia in some animals) compared with wild-type or heterozygous males." (PMID 16759351, 2006).
bone osteosarcoma (1 paper, 2020). A usually aggressive malignant bone-forming mesenchymal neoplasm arising from the bone. "Strikingly, the widely used human bone osteosarcoma U2OS cells show no detectable effect on resection upon SKP2 depletion." (PMID 32683422, 2020).
breast invasive ductal carcinoma (1 paper, 2012). "In the present study, we immunohistochemically determined the subcellular expression of Skp2 in invasive ductal carcinomas of the breast and studied its clinicopathological significance." (PMID 23300741, 2012). "The Kaplan-Meier curve and log-rank test analyses revealed that cytoplasmic Skp2 expression was significantly associated with DFS (log rank = 5.091, p = 0.024), and OS (log rank = 7.892, p = 0.005) in all breast invasive ductal carcinoma patients." (PMID 23300741, 2012).
cholangiocarcinoma (1 paper, 2015). A carcinoma that arises from the intrahepatic biliary tree (intrahepatic cholangiocarcinoma) or from the junction, or adjacent to the junction, of the right and left hepatic ducts (hilar cholangiocarcinoma). "The vast majority of malignant tumors were in fact HCC, whereas cholangiocarcinomas (CCA) rarely occurred in SKP2/myr-AKT1 mice, in accordance to that described for myr-AKT1 mice." (PMID 25537506, 2015).
Chronic Heart Failure (1 paper, 2022). "SKP2 was targeted by miR-21-5p and it was down-regulated in chronic heart failure rats and doxorubicin-induced cardiomyocytes." (PMID 35865382, 2022). "Paeonol showed cardioprotective effects on doxorubicin-induced chronic heart failure via regulating miR-21-5p/SKP2/PI3K/AKT axis." (PMID 35865382, 2022).
ciliopathy (1 paper, 2022). A genetic disorder of the cellular cilia or the cilia anchoring structures, the basal bodies, or of ciliary function. "Restoring ER homeostasis and/or interfering with SKP2-YAP interaction represent therapeutic approaches that could stem the progression of cyst growth in ciliopathy-related cystic kidney disease." (PMID 36326820, 2022). "Our demonstration that SKP2 levels were also increased in Pkd1-null kidneys points to the wider applicability of our findings in other forms of ciliopathy-related kidney cyst disease, as opposed to being viewed as a select consequence of the jck mutation." (PMID 36326820, 2022).
colonic adenocarcinoma (1 paper, 2011). "Furthermore, high levels of activation of Akt correlate with the cytosolic accumulation of Skp2 in human colonic adenocarcinoma." (PMID 21386910, 2011).
cyst (1 paper, 2022). A sac-like closed membranous structure that may be empty or contain fluid or amorphous material. "In parallel, SKP2-mediated K48-linked polyubiquitination targets p27 for proteolysis, thereby contributing to the dysregulation of the cell cycle and the observed hyperproliferative state of the cyst lining cells." (PMID 36326820, 2022). "Importantly, pharmacological tuning down of ER stress and the ISR leads to decreased YAP and SKP2 expression and impaired cyst progression, thereby highlighting the potential clinical utility of targeting this pathway in PKD." (PMID 36326820, 2022).
depression (1 paper, 2023). "Recently, Skp2 has been reported to be a therapeutic target in other non-cancer diseases, such as BM transplantation, depression." (PMID 37089937, 2023).
endothelial dysfunction (1 paper, 2020). In vascular diseases, endothelial dysfunction is a systemic pathological state of the endothelium (the inner lining of blood vessels) and can be broadly defined as an imbalance between vasodilating and vasoconstricting substances produced by (or acting on) the endothelium. "Despite its failure to rescue Sirt1 and eNOS, ectopic Skp2 expression significantly limited the increase of PAI-1 level, which is a crucial maker for endothelial dysfunction." (PMID 32313103, 2020).
epithelial ovarian tumors (1 paper, 2010). "In one study, Skp2 expression correlated with reduced p27 in epithelial ovarian tumors, and although Skp2 alone was associated with poor prognosis, evaluation of the combined phenotype, Skp2(+) Jab1/CSN5(+) p27(-), led to identification of patients with the worst prognosis." (PMID 20955608, 2010).
fungal infection (1 paper, 2012). "The induction of p52- and p65-heterodimers by fungal infection could therefore explain in part the down-regulation of cyclin-D1, -E and Skp2." (PMID 22396644, 2012).
Giardia infection (1 paper, 2023). "The mRNA levels of Ufd1 and Skp2 were decreased during Giardia infection, and Skp2 regulated the expressions of p21 and p27 when judged with siRNA knockdown experiments." (PMID 37006313, 2023).
hyperplasia (1 paper, 2026). An abnormal increase in the number of cells in an organ or a tissue with consequent enlargement. "IHC analysis reveals that strong SKP2 positive staining was mainly observed at the sites of prostatic lesions (i.e. hyperplasia, PINs and low-grade carcinoma), accompanied by decreased staining intensities of p27Kip1 in probasin-hSKP2-KI mice compared to those from wild-type mice." (PMID 41542047, 2026).
megakaryoblastic leukemia (1 paper, 2016). "In UT-7, a cell line derived from a megakaryoblastic leukemia, the effect of BuA on Skp2 was, however, not noticeable." (PMID 26682002, 2016).
mesenchymal neoplasms (1 paper, 2008). "The direct correlation between expression of Ki67 and Skp2 was significant, in agreement with what has been found in several tumour types, including mesenchymal neoplasms." (PMID 18474118, 2008).
myeloid leukemia (1 paper, 2016). A clonal proliferation of myeloid cells and their precursors in the bone marrow, peripheral blood, and spleen. "Accordingly, we found increased Cdh1 expression upon Skp2-kd in HL-60 and NB4 myeloid leukemia cells." (PMID 27374082, 2016).
Obesity (1 paper, 2021). Accumulation of substantial excess body fat. "Moreover, CUL1 (along with SKP1 (S-phase-kinase-associated protein 1) and F-Box protein) forms the largest E3 ubiquitin ligase family (Skp1-Cullin1-F-box (SCF)) E3 ligase is known for controlling obesity with an association of Skp2." (PMID 33669862, 2021).
papillary thyroid cancers (1 paper, 2022). "Recently, a research team found that SKP2 is overexpressed in 45.5% of papillary thyroid cancers and that SKP2 expression is also significantly associated with extrathyroidal extension and distant metastasis." (PMID 35313079, 2022). "In this study, the combination of bortezomib and TRAIL induced a synergistic apoptotic response and suppressed cancer/tumor growth of papillary thyroid cancers in vitro and in animal models, suggesting that SKP2 is a potential therapeutic target in aggressive papillary thyroid cancers." (PMID 35313079, 2022).
Parkinson disease (1 paper, 2008). A progressive degenerative disorder of the central nervous system characterized by loss of dopamine producing neurons in the substantia nigra and the presence of Lewy bodies in the substantia nigra and locus coeruleus. "Well known examples are deregulation of the E3s BRCA1, Mdm2, VHL and Skp2 in various cancers, and Parkin in Parkinson's disease." (PMID 18213395, 2008).
Pca (1 paper, 2020). "Safranal downregulates mRNA and protein levels of Skp2 during cell cycle re-entry, which plausibly reduces the risk of Pca recurrence." (PMID 33392189, 2020).